GAS5 (growth arrest specific 5)
Diseases named in the same sentence as GAS5 in open-access papers (continued):
Sharing a sentence is not in itself a finding about the gene and the disease.
tumor (continued). "A lower expression of GAS5 is associated with large tumor size, low histological grade and advanced TNM stage and GAS5 expression is an independent predictor for overall survival in CRC patients." (PMID 28108736, 2017). "Many studies have shown that GAS5 induced inhibitory effect on the migration and invasion of different types of tumor cells in vitro and in vivo, including renal cell carcinoma, lung cancer, hepatocellular carcinoma, ovarian cancer, cervical cancer." (PMID 29225772, 2017). "Compared to the high GAS5 expression group, additionally, patients with low GAS5 expression in tumor tissues were more prone to lymph node metastasis (OR = 0.234, 95%CI: 0.153–0.358, P < 0.001) and high tumor stage (OR = 0.185, 95% CI:0.102–0.333, P < 0.001)." (PMID 29163187, 2017). "Long non-coding RNA growth arrest-specific transcript 5 (lncRNA GAS5) is a well-known tumor suppressor in the pathogenesis of a variety of human cancers." (PMID 29225772, 2017). "Several studies also demonstrated that upregulation of GAS5 expression inhibits tumor cell proliferation and promotes apoptosis." (PMID 29029523, 2017). "The results indicated that decreased GAS5 expression is significantly correlated with unfavorable clinical prognosis in patients with various tumor types." (PMID 29029523, 2017). "GAS5 has been suggested to inhibit the migration and invasion of many types of tumor cells, but the inhibitory effect of GAS5 on PC cell migration and invasion was first reported in this work." (PMID 29225772, 2017). "GAS5, acts as a tumor suppressor, has been shown to be extensively involved in the proliferation, apoptosis, migration and invasion of tumor cells." (PMID 29225772, 2017). "LncRNA GAS5 plays a tumor suppressive role in a variety of human cancers and promises to be a novel diagnostic biomarker, therapy target, as well as prognostic biomarker." (PMID 28977945, 2017). "The expression of miR-32-5p was markedly inhibited in GAS5-over-expressed tumor tissue, whereas both PTEN mRNA and protein levels were increased." (PMID 29225772, 2017). "The growth arrest-specific transcript 5 (GAS5) is a rising star among tumor-suppressive lncRNAs among all the kinds of lncRNAs." (PMID 29163187, 2017). "These discoveries are consistent with lncRNA GAS5 being a ubiquitous tumor suppressor and prognosis marker." (PMID 29029523, 2017). "In conclusion, our meta-analysis indicates that decreased GAS5 expression is positively correlated with poor tumor differentiation, larger tumor size, and advanced clinical stage." (PMID 29029523, 2017). "PTEN, a well-known tumor suppressor that is competitively regulated by GAS5 in the subpathway region, inhibits the cancer-related IGF-1/mTOR pathway." (PMID 28152521, 2017). "First described as a tumor suppressor in 1988, the Growth Arrest-Specific transcript 5 (GAS5) is a 630 nt long non-coding transcript transcribed by a gene located in chromosome 1q25." (PMID 27148353, 2016). "we also examined expression level of GAS5 in CRC tumor tissues and adjacent normal tissues of 50 CRC cases." (PMID 27863421, 2016). "A tumour suppressor role for GAS5 lncRNA is further indicated by its inhibition of tumour growth in xenograft models of breast and other cancers." (PMID 26862727, 2016). "GAS5 (growth arrest-specific 5) is a potential tumour suppressor factor that negatively regulates CDK6 and is significantly decreased in PDAC tissues compared to untransformed tissues." (PMID 27689078, 2016). "To determine the role of GAS5 in tumor metastasis in vivo, we injected 2.5 × 106 si-GAS5 stably transfected SKBR-3 cells into the tail veins of SCID mice." (PMID 27034004, 2016). "The basis for this tumour suppressor function has been ascribed to the apoptosis-promoting activity of GAS5 lncRNA, which has itself been shown to reside within the HREM portion of the GAS5 lncRNA molecule in breast and other cells." (PMID 26862727, 2016).
tumor (continued). "Then the associations between GAS5 rs145204276 and CRC susceptibility were analyzed stratified by Tumor site." (PMID 27863421, 2016). "The lncRNA growth arrest special 5 (GAS5), was previously identified to be down-regulated and functions as a tumor suppressor gene in many kinds of cancers." (PMID 27863421, 2016). "Our finding that GAS5 is highly expressed in hESCs appears to be arbitrary given its significant effect on tumour suppression and proliferation inhibition." (PMID 27811843, 2016). "GAS5 knockdown increased cell proliferation and tumor growth in vivo and low levels of GAS5 correlated with histological grade and advanced TNM stage." (PMID 27608009, 2016). "Previous studies showed that GAS5 functions as a ceRNA for miR-21, and that miR-21 promoted tumor proliferation and invasion by targeting PTEN." (PMID 27034004, 2016). "Growth Arrest Specific 5 (GAS5) is a cell-cycle arrest and apoptosis-related lncRNA with tumor suppressor activity." (PMID 27177333, 2016). "GAS5 expression is typically reduced in such cancers and clinico-pathological characteristics, such as tumour size, staging, invasion and/or regional lymph node metastasis, show disease-specific inverse correlations with GAS5 levels." (PMID 26198250, 2015). "Specially, GAS5 has been supposed to play a tumor-suppressive role and was down-regulated in many cancers." (PMID 26511107, 2015). "The quantitative reverse-transcriptase polymerase chain reaction (qRT-PCR) technique was used to assess GAS5 expression in tumor samples and their corresponding adjacent normal tissues in a total of 99 paired samples." (PMID 25925741, 2015). "The GAS5 overexpression treatment dramatically decreased the tumor size and weight compared with the control group and the gefitinib only group." (PMID 25925741, 2015). "One such example is GAS5 (growth arrest-specific 5), a tumor suppressor lncRNA which reduces growth, metabolism, and sensitizes cells to apoptosis by inhibiting glucocorticoid receptor." (PMID 25954300, 2015). "The downregulation of GAS5 expression is thought to contribute to tumor formation and to affect proliferation and apoptosis." (PMID 25925741, 2015). "Previous studies have provided some clues regarding the mechanism by which lncRNA GAS5 confers tumor suppression." (PMID 25959498, 2015). "The examination of the correlation between the clinicopathological features and GAS5 expression levels showed that decreased GAS5 expression was correlated with a larger tumor size, poorer differentiation, and more advanced tumor-node-metastasis (TNM) staging." (PMID 25925741, 2015). "As will be discussed here, more recent work has shown that GAS5 lncRNA is dysregulated in multiple cancers and confirm a tumour suppressor role for this molecule." (PMID 26198250, 2015). "A lower expression of GAS5 was detected in tumor of larger size, higher tumor stage, deeper depth of invasion and more regional lymph nodes." (PMID 24884417, 2014). "GAS5 is a long ncRNA (~650 bases in humans) that was originally isolated from a screen for potential tumor suppressor genes expressed at high levels during growth arrest." (PMID 24884417, 2014). "The low-GAS5 group was correlated with larger tumor size (p = 0.008), higher TNM stage (P < 0.001), deeper depth of invasion (P < 0.001) and more regional lymph nodes (P < 0.001) than the high-GAS5 group." (PMID 24884417, 2014). "LncRNAs that function as tumor suppressors are, for example, growth arrest-specific 5 (GAS5), which is aberrantly expressed in several cancers including PCa and the pseudogene PTENP1." (PMID 25243154, 2014). "The results showed that the levels of GAS5 expression in tumor tissues formed from pCDNA3.1-GAS5 cells were higher than those of tumors formed in control group." (PMID 24884417, 2014).
tumor (continued). "In cancer, expression of tumour suppressor lncRNAs, such as GAS5 or MEG3, should decrease tumour growth." (PMID 23887658, 2013). "Cells which fail to express GAS5 will evade apoptosis in response to the stressful stimuli, which a tumour cell would experience in a poorly vascularised microenvironment, intermittently depleted of nutrients and oxygen." (PMID 21407217, 2011). "Additionally, Eisa A reported that the expression of GAS5 correlates with patients' age, gender, ethnicity, and tumor stage in HCC." (PMID 41474641, 2026). "The interplay between Humanin, MOTS-c, GAS5, and these miRNAs is of particular interest: they may operate within a regulatory axis affecting mitochondrial metabolism, inflammation, and tumor progression." (PMID 40768089, 2025). "GAS5 sponges miR-21 to suppress oncogenic signaling pathways and facilitate tumor suppression." (PMID 39958058, 2025). "This persistent anti-tumor activity of GAS5 across various cancer types suggests that strategies aimed at upregulating GAS5 expression could represent a promising therapeutic approach in oncology." (PMID 39941145, 2025). "Approaches such as miR-423-3p mimics or small molecules that inhibit the ability of GAS5 to sponge miR-423-3p could potentially restore the tumor-suppressive activity of miR-423-3p and reduce SMARCA4 levels, thereby inhibiting HCC growth and progression." (PMID 40451925, 2025). "GAS5 is downregulated in human CRC tissues in comparison to tumour-adjacent normal tissues." (PMID 40362348, 2025). "It has also been shown that GAS5 can mediate tumor-suppressor function by inhibiting the expression levels of the distal gene hnRNPK1, thereby inhibiting the AKT pathway and/or promoting the expression of the pro-apoptotic Bcl-2 family proteins BAK and BAX in OC cells." (PMID 39941838, 2025). "A decrease in GAS5 may impair this regulatory function, allowing miR-21 and miR-103 to promote tumor progression unchecked." (PMID 40768089, 2025). "Conversely, GAS5 functions as a tumor suppressor by inducing apoptosis and inhibiting cell growth." (PMID 39895777, 2025). "Besides acting as a tumour-promoter, lncRNAs such as lncRNA GAS5 can act as a tumour suppressor by sponging tumour-enhancing miRNA, e.g., miR-23 in ovarian cancer." (PMID 39736850, 2025). "Conversely, GAS5 acts by sponging miR-21, which has been reported to negatively regulate T cell activation, suggesting that GAS5 downregulation in the tumor microenvironment may promote miR-21 activity and, therefore, impair T cell activation." (PMID 40429961, 2025). "Although the binding of GAS5 to YAP promotes its phosphorylation and ubiquitylation for degradation, loss of GAS5 lifts the restraint on YAP signaling, resulting in enhancement of cell proliferation, migration, and further in vivo tumor progression." (PMID 41301491, 2025). "Among other tumour-suppressive lncRNAs, GAS5 stands out as most similar to MEG3." (PMID 40242248, 2025). "Finally, GAS5, a tumor‐suppressive circulating lncRNA, plays an essential role in inhibiting cancer cell growth by acting as a decoy for glucocorticoid response elements and modulating apoptotic pathways." (PMID 41031251, 2025). "Low levels of GAS5 were positively correlated with large tumour size and poor overall survival." (PMID 40362348, 2025). "Disruption of this m6A modification pathway could therefore reduce GAS5 levels and inhibit tumor progression." (PMID 40451925, 2025). "At the same time, GAS5 expression is suppressed in these tumor cells." (PMID 41226688, 2025). "However, GAS5’s tumor-suppressing function extends beyond its inverse correlation with miR-21, as it also modulates cancer progression through various miRNA-mediated signaling pathways." (PMID 39941145, 2025).
tumor (continued). "A recent study demonstrated the ability of sorafenib-induced EVs, which were enriched with tumor suppressor ncRNAs such as GAS5, to significantly reduce xenograft tumor area, suppress angiogenesis, and reduce the number of micrometastases in the tails of zebra fish." (PMID 39941145, 2025). "However, GAS5 exerts its tumor-suppressive effects by interacting with the PI3K/AKT/mTOR pathway through the upregulation of PTEN and the direct inhibition of AKT activation." (PMID 40142329, 2025). "It is interesting to note that some lncRNAs such as HOTAIR, ANRIL, GAS5, NEAT1, CCAT2, UCA1 are consistently reported to be associated with several prognostic indicators such as advanced FIGO stage, increased tumour growth, lymph node metastasis and lowered survival measures." (PMID 39912983, 2025). "In addition, the GSE213324 dataset of KIRC, which consists of 21 tumor samples and 20 adjacent tissues, shows significant upregulation (∣Log2FC∣ = 0.816, adjusted p = 0.00463) of GAS5." (PMID 39958058, 2025). "Additionally, the mitochondria-localized lncRNA growth-arrest-specific 5 (GAS5) has been identified as a tumor suppressor that plays a critical role in maintaining cellular energy homeostasis." (PMID 39403599, 2024). "Accordingly, xenograft assay showed that GAS5 overexpression attenuated tumor growth, while GAS5 silencing promoted tumor growth in vivo, which could be reversed by knockdown or overexpression of IGF2BP2 or QKI." (PMID 38782769, 2024). "GAS5 (growth arrest specific 5) is a GBM tumour suppressor lncRNA." (PMID 38790894, 2024). "GAS5 regulates genes associated with tumor metastasis, including those involved in the EMT process, influencing the invasiveness and metastatic capabilities of tumor cells." (PMID 39286016, 2024). "According to reports, GAS5 acts as a tumor suppressor in several malignancies." (PMID 39170516, 2024). "Furthermore, overexpression of FTO attenuated the inhibitory effect of GAS5 on tumor growth in vivo." (PMID 38782769, 2024). "GAS5 is another tumor suppressor lncRNA, which is located on chromosome 1q25.1." (PMID 38059120, 2024). "The lncRNA GAS5 plays an important tumor suppressor role in PC." (PMID 39857631, 2024). "Results suggested that the influence of GAS5 on the migration of macrophages and PBMCs was partly reversed with the addition of these neutralizing antibodies, indicating that type I interferon signaling mediated tumor cell-derived GAS5’s regulatory effect on immune cell infiltration." (PMID 38762546, 2024). "Taken together, our results indicated that tumor cell-derived GAS5 could enhance immune cell recruitment and suppress tumor development in NSCLC." (PMID 38762546, 2024). "Reduced levels of noncoding RNA GAS5 in exosomes found in the bloodstream (Exo-GAS5) may serve as a non-invasive blood-based tumour marker for early-stage NSCLC diagnosis." (PMID 39464709, 2024). "As a tumor-suppressive transcript, therapeutic approaches aimed at augmenting GAS5 expression in BC may be crucial in the development of novel drugs." (PMID 37444428, 2023). "At the time of writing this review, we found five studies on BC reporting that GAS5 acts as a ceRNA for four miRNAs with oncogenic functions (onco-miRs), including miR-21-5p, miR-221-3p, miR-196a-5p, and miR-378-5p, and the tumor-suppressor miR-216b." (PMID 37444428, 2023).
tumor (continued). "Besides GAS5, other lncRNAs have been studied for their tumor-suppressive functions, such as MEG3 and TUG1, reviewed elsewhere." (PMID 37370745, 2023). "Epidermal growth factor receptor (EGFR) wild type lung adenocarcinoma, the GAS5 SNP rs145204276, may aid in tumor stage, distal metastases, and lymph node metastasis prediction." (PMID 37888204, 2023). "Furthermore, IHC analysis showed that the expression of drug resistance-related proteins was higher in tumor tissues of mice that had been treated with 7721/sora-RBM38-OE + GAS5-KD cells than in those treated with 7721/sora-RBM38-OE cells." (PMID 37296859, 2023). "Finally, GSTM3 is regulated by lncRNA GAS5, a tumor suppressor that acts on tumor cells repressing proliferation, migration, and invasion, and promoting apoptosis and reactive oxygen species (ROS)." (PMID 37047296, 2023). "GAS5 is downregulated in various cancers and acts as a tumor suppressor in BC." (PMID 37175800, 2023). "In a variety of tumors, the expression of GAS5 was significantly decreased, suggesting that GAS5 might be a tumor-suppressing LncRNA." (PMID 37639158, 2023). "Finally, it should be noted that the opposing roles of ANRIL and GAS5 as tumor promoter versus tumor suppressor likely reflect the ambivalent role of PROX1 in cancer." (PMID 37407839, 2023). "Moreover, decreased expression of growth arrest specific transcript 5 (GAS5) in PA induces tumor aggressive behavior and metastasis." (PMID 38204968, 2023). "As GAS5 downregulation is associated with poor prognosis in NSCLC, the effects of VRB could potentially aggravate the tumor and induce further metastasis." (PMID 38137519, 2023). "Additionally, low GAS5 expression was correlated with larger tumor size, lower differentiation levels, and higher staging of tumor–node metastasis." (PMID 37370745, 2023). "The GAS5 tumor-suppressor lncRNA also directly controls transcription." (PMID 37444543, 2023). "A tumour-suppressive role in LC (NSCLC) was discovered for GAS5 (growth arrest-specific 5) lncRNA." (PMID 38203731, 2023). "The question of whether GAS5 lncRNA regulates multiple genes, thereby contributing to its tumor-suppressive phenotype, remains unanswered, leaving a wide area for investigation." (PMID 38139448, 2023). "In cervical cancer (CC), knockdown of YTHDF2 significantly increased the expression and stability of GAS5, a tumor suppressor gene, thereby inhibiting the proliferation, migration and invasion of CC cells in vitro and suppressing the tumor growth and metastasis of CC in vivo." (PMID 35382893, 2022). "Growth arrest-specific 5 (GAS5) is another well-characterized tumour suppressive lncRNA." (PMID 35159022, 2022). "GAS5 is a tumor suppressor whose expression level increases during growth stagnation." (PMID 35692795, 2022). "Moreover, the TCGA data also showed again that ZFAS1, EBLN3P, or GAS5 was overexpressed in PCa tumor compared to adjacent normal samples." (PMID 36514044, 2022). "Accordingly, compared with the control group, tumor weight in the GAS5 overexpression group showed a significant decrease after 4 weeks, while either miR-27a-5p overexpression or sh-CYLD could reverse the inhibitory effect of GAS5 on tumor weight." (PMID 35435104, 2022). "On the other side, all the ratios of worse tumor statuses including tumor stage, tumor T status, lymph node status and distal metastases were silently higher with the presence of GAS5 SNP rs145204276 Ins/Del + Del/Del compared to the GAS5 SNP rs145204276 Ins/Ins wild type." (PMID 36011604, 2022). "Expression levels of NEAT1 and GAS5 were also significantly increased in tumor samples compared with adjacent normal tissue (p-value = 2.16e−8 for GAS5 and p-value = 0.01 for NEAT1, t-test), suggesting that they inhibit apoptosis in HCC, perhaps by interacting with EZH2 and JARID2." (PMID 36578923, 2022).